CACNA1A (calcium voltage-gated channel subunit alpha1 A)
Diseases named in the same sentence as CACNA1A in open-access papers (continued):
Sharing a sentence is not in itself a finding about the gene and the disease.
familial hemiplegic migraine type 1 (continued). "Mutations in the CACNA1A gene have been found to be responsible for three disorders with autosomal dominant inheritance: EA2 (MIM: 108500), familial hemiplegic migraine type 1 (FHM1; MIM: 141500), and spinocerebellar ataxia type 6 (SCA6; MIM: 183086)." (PMID 27066515, 2016). "However, heterozygous mutations in the CACNA1A gene have also been identified in spinocerebellar ataxia type 6 (SCA6, MIM 183086) and familial hemiplegic migraine type 1 (FHM1, MIM 141500), which share with EA2 the allelic autosomal dominant mode of inheritance." (PMID 32471306, 2020).
spinocerebellar ataxia type 6 (68 papers, 2005 to 2026). Spinocerebellar ataxia type 6 (SCA6) is the most common subtype of autosomal dominant cerebellar ataxia type III (ADCA type III) characterized by late-onset and slowly progressive gait ataxia and other cerebellar signs such as impaired muscle coordination and nystagmus. "Spinocerebellar Ataxia Type 6 (SCA6) is caused by an expansion of the CAG codons in exon 47 of the 3′ region of the CACNA1A gene, which codes for brain-specific, voltage-dependent calcium channels that are often found in Purkinje cells." (PMID 38921455, 2024). "One such protein we identified is Cacna1a, a α1A-subunit of voltage-gated P/Q-type calcium channels (Cav2.1), which contains a mutation that causes spinocerebellar ataxia type 6 (SCA6) and episodic ataxia type 250,51." (PMID 35614064, 2022). "Spinocerebellar ataxia type 6 (SCA6) is caused by mutations leading to CAG repeats (20 or more) in the CACNA1A gene that encodes the α1A voltage-dependent calcium channel subunit." (PMID 33671313, 2021). "Abnormal trinucleotide repeat expansion in the CACNA1A gene causes spinocerebellar ataxia type 6 (SCA6, OMIM #183086), which normally presents in adulthood with progressive gait ataxia, incoordination, tremors, dysarthria, and nystagmus (Case y & Gomez, 1998)." (PMID 32692472, 2020). "Spinocerebellar ataxia type 6 (SCA6) is an age-dependent neurodegenerative disease caused by anomalous expansion in the CAG triplet repeat in the gene CACNA1A." (PMID 27979829, 2016). "Mutations in the CACNA1A gene are implicated as causal for spinocerebellar ataxia type 6 in humans." (PMID 37510383, 2023). "CACNA1A, on the other hand, is known to be directly involved in spinocerebellar ataxia type 6 (SCA6), where several DNA variants directly cause the disease." (PMID 41345545, 2025). "Spinocerebellar ataxia type 6 (SCA6) is due to a CAG repeat expansion in the CACNA1A gene encoding the alpha 1A-voltage-dependent calcium channel (CaV2.1)." (PMID 26331028, 2014). "For example, in spinocerebellar ataxia type 6 (SCA6), mutations in the CACNA1A gene cause the expansion of CAG repeats, which results in the formation of abnormal proteins with long glutamine sequences." (PMID 40869402, 2025). "Spinocerebellar ataxia type 6 (SCA6), characterized by progressive cerebellar ataxia, is caused by an expansion of a CAG repeat in the terminal portion of CACNA1A, which results in toxic degeneration of cerebellar Purkinje cells." (PMID 36800925, 2023). "Mutations in the CACNA1A gene that encodes the pore-forming CaV2.1 α1 subunit cause three neurological disorders: familial hemiplegic migraine type 1 (FHM1), spinocerebellar ataxia type 6 (SCA6) and Episodic ataxia 2 (EA2)." (PMID 27260834, 2016). "A third disorder—spinocerebellar ataxia type 6 (SCA6)—results from poly-glutamine (polyQ) expansion in the CACNA1A gene product." (PMID 24592212, 2014). "EA2 is caused by heterozygous mutations in CACNA1A, which are also responsible for familial hemiplegic migraine type-1 (FHM1) and spinocerebellar ataxia type-6 (SCA 6)." (PMID 23441182, 2013). "Interestingly, the CACNA1A gene is subject to CAG repeat expansion, where it causes spinocerebellar ataxia type 6." (PMID 40169779, 2025). "Furthermore, the CACNA1A gene and the FIG4 gene are both implicated as causal for progressive neurodegenerative skeletal muscular diseases in humans, and spinocerebellar ataxia type 6 and Charcot-Marie-Tooth Neuropathy Type 4J, respectively." (PMID 37510383, 2023). "Interestingly, a late-onset chronic disorder, the spinocerebellar ataxia type 6 (SCA6), has been also linked to CACNA1A variants." (PMID 33544220, 2021). "In addition to EA2, there are two more allelic disorders caused by CACNA1A mutations with autosomal dominant pattern of inheritance: familial hemiplegic migraine type 1 (FHM1) and spinocerebellar ataxia type 6 (SCA6)." (PMID 33105744, 2020).
spinocerebellar ataxia type 6 (continued). "Interestingly, this analysis revealed that the coverage and the genotyping quality for coding RED loci were good (>20×) across all genes, with the exception of CACNA1A, ATXN2 and HTT, which cause spinocerebellar ataxia 2, spinocerebellar ataxia 6 and Huntington disease, respectively." (PMID 40004498, 2025). "Spinocerebellar ataxia type 6 was first described in 1997 when researchers from the USA discovered that three different protein isoforms of the human α1A voltage-dependent calcium channel subunit (CACNA1A) contained a polymorphic CAG repeat expansion towards the C-terminal of the protein." (PMID 34829728, 2021). "Expansion of the CAG repeat in the α1A subunit of the voltage-dependent calcium channel gene CACNA1A, leads to the Spinocerebellar ataxia type 6 (SCA6, MIM 183086)." (PMID 30167989, 2018). "Mutations in CACNA1A contribute also to episodic ataxia (EA2; MIM108500) and spinocerebellar ataxia type 6 (SCA6; MIM183086)." (PMID 26747084, 2016). "Already in 1997, a third disease, the spinocerebellar ataxia type 6 (SCA6), was mapped to CACNA1A locus." (PMID 33737904, 2021). "Spinocerebellar ataxia type 6 (SCA6) is an autosomal dominant disorder characterized by a late onset slowly progressive ataxia, dysarthria and nystagmus associated with an abnormal CAG expansion in exon 47 of CACNA1A gene." (PMID 22379397, 2011). "Spinocerebellar ataxia type 6 (SCA6), characterized by an abnormal CAG trinucleotide repeat expansion in CACNA1A gene, shows an estimated prevalence of about 0.02 on 100,000 individuals." (PMID 33733696, 2021).
dentatorubral-pallidoluysian atrophy (33 papers, 2005 to 2025). Dentatorubral pallidoluysian atrophy (DRPLA) is a rare subtype of type I autosomal dominant cerebellar ataxia (ADCA type I). "Interestingly, CACNA1A variants were one of the most prevalent causes of AD-HCA, after SCA3 and dentatorubral-pallidoluysian atrophy (DRPLA), in our population-based survey." (PMID 35326432, 2022).
developmental delay (32 papers, 2015 to 2025). "Here, we describe a case of CACNA1A-associated disease in a boy with developmental delay and congenital ataxia who developed recurrent status epilepticus and life-threatening postictal apnea after the age of 6 years." (PMID 40703772, 2025). "Lately, the spreading of next generation sequencing techniques linked de novo CACNA1A variants to an even broader phenotypic spectrum including early developmental delay, autism spectrum disorders, epileptic encephalopathy, and early onset paroxysmal dystonia." (PMID 33737904, 2021). "In the last decade, a syndrome with severe developmental delay and dysmorphic features has been described in association with microdeletion of chromosome 19 (19p13.13 or 19p13.2) containing also the CACNA1A gene." (PMID 33737904, 2021). "In recent years, CACNA1A has become associated with a multitude of neurological phenotypes, including congenital hypotonia, cerebellar hypoplasia, cognitive delay, refractory epilepsy, and stroke." (PMID 32692472, 2020). "In 2019, 18 children with CACNA1A mutations were reported, and 9 out of 18 patients presented with cognitive impairment, including developmental delay, cognitive difficulties, and learning difficulties." (PMID 33425808, 2020). "Rare cases of markedly severe early onset developmental delay and congenital ataxia can be due to de novo CACNA1A missense alleles, with variants affecting the S4 transmembrane segments of the channel, some of which are reported to be loss-of-function." (PMID 28742085, 2017). "We ascertained 5 individuals who underwent exome sequencing for global developmental delay and congenital ataxia, in whom de novo missense variants in CACNA1A were discovered." (PMID 28742085, 2017). "Individuals carrying CACNA1A mutations were shown to present congenital ataxia, cerebellar atrophy and developmental delay, sharing some clinical features of autism." (PMID 26566276, 2015). "The CACNA1A-associated phenotypic spectrum is really much more wider comprising early developmental delay, autism spectrum disorders, epileptic encephalopathy, and early onset paroxysmal dystonia, as revealed by the detection of mutations facilitated by the use of NGS-based genetic diagnostic tools." (PMID 38003592, 2023). "Indeed, several studies applying NGS discovered pathogenic CACNA1A variants in children with severe psychomotor delay born from healthy parents." (PMID 33737904, 2021). "However, with advanced next-generation sequencing techniques, CACNA1A variants have been linked to more wider phenotypic spectrum including global developmental delay (GDD)/intellectual disability (ID), epileptic encephalopathy (EE), and autism spectrum disorder (ASD)." (PMID 37555011, 2023). "We analyzed the allele frequencies of nine single-nucleotide polymorphisms (SNPs) in the CACNA1A, CACNA1C, and CACNA1H genes among pediatric patients with developmental delay/intellectual disability (DD/ID)." (PMID 40725423, 2025). "The majority of patients however showed the first signs of CACNA1A disease, consisting of developmental delay or episodic symptoms, early in life." (PMID 39110218, 2024). "Recent studies indicate that neuropsychiatric and developmental symptoms are common in patients with episodic CACNA1A disorders and should be considered in the differential diagnosis of otherwise unexplained developmental delay." (PMID 33746731, 2021). "Finally, compound heterozygous mutations in the CACNA1A gene encoding the pore-forming α1A subunit of the CaV2.1 voltage-gated calcium channel have been reported to cause epileptic encephalopathy with progressive cerebral atrophy, optic nerve atrophy, hypotonia, and severe developmental delay." (PMID 32176688, 2020). "Among the CACNA1A-related phenotypes, our results suggest that non-progressive congenital ataxia is associated with developmental delay and dysmorphic features, constituting a recognizable syndromic neurodevelopmental disorder." (PMID 34068417, 2021).
developmental delay (continued). "After the initial association of CACNA1A SNVs with human disease in a landmark study, a number of reports noticed the recurrence of early onset phenotypes with developmental delay, intellectual disability, ADHD, ADS in the offspring of CACNA1A families." (PMID 40095113, 2025). "Genotype–phenotype correlations of the CACNA1A-related neurodevelopmental disorders such as global developmental delay (GDD)/intellectual disability (ID), epileptic encephalopathy (EE), and autism spectrum disorder (ASD) are unknown." (PMID 37555011, 2023).
Cerebellar atrophy (30 papers, 2012 to 2025). Cerebellar atrophy is defined as a cerebellum with initially normal structures, in a posterior fossa with normal size, which displays enlarged fissures (interfolial spaces) in comparison to the foliae secondary to loss of tissue. "Different genetic variants of the CACNA1A gene are not only implicated in causing more severe cerebellar atrophy, but can also be associated with early onset." (PMID 38785745, 2024). "Paradoxically, however, the degenerative phenotype resulting from Cacna1a loss-of-function is more prominent in mice as compared to humans where it causes primarily an episodic disorder with variable and late onset of cerebellar atrophy." (PMID 35757096, 2022). "In conclusion, we provide further evidence that biallelic CACNA1A variants can cause a severe epileptic and developmental encephalopathy with progressive cerebellar atrophy, and highlight complexities of genetic counseling in such situations." (PMID 36063114, 2022). "Six out of 12 cases with CACNA1A variants and ID showed statistically significant association with cerebellar atrophy according to one study." (PMID 33985586, 2021). "Two CACNA1A mutated patients showed cerebellar atrophy signs (1/2 pancerebellar atrophy with clinical signs of congenital ataxia, 1/2 hypoplasia of superior vermis folia with no clinical signs)." (PMID 31681150, 2019). "Moreover, we have recently described two sibs with bi-allelic CACNA1A pathogenic variants, which cause early onset epileptic encephalopathy, cerebral, cerebellar atrophy and optic nerve atrophy." (PMID 27956814, 2016). "For example, the tottering mutation (Cacna1atg) that occurs in the Cacna1a for the CaV2.1 subunit gives rise to polyspike discharges and behavioral absence seizures, while the leaner mutation in the same gene leads to cortical spike-wave discharges in the animals with cerebellar atrophy." (PMID 36142719, 2022). "Progressive cerebellar atrophy was associated with progressive ataxia only in four cases (40%; ATM, CACNA1A, FXN, and SAMD9L)." (PMID 40326640, 2025). "A small study of children with CACNA1A and EA or other paroxysmal events commonly had cognitive impairment, more likely when cerebellar atrophy was present on MRI." (PMID 37008993, 2023). "A brain MRI scan was performed in 9 patients carrying CACNA1A mutation showing no cerebellar atrophy." (PMID 34320921, 2021). "CACNA1A dysfunction might lead to cerebellar atrophy and functional deficits of the cerebellum, which usually are detected in autistic patients." (PMID 26566276, 2015).
channelopathy (29 papers, 2008 to 2025). Channelopathies are a group of diseases caused by the dysfunction of ion channel subunits or their interacting proteins. "For example, ATN1 and HTT have been linked to neurodevelopmental disorders, while CACNA1A has been linked to channelopathies with diverse neurological manifestations." (PMID 41254939, 2025). "This monocentric study provides insights on the electrophysiological signature associated with two rare neurogenetic channelopathies: CACNA1A- and GAA-FGF14-related disorders." (PMID 41240219, 2025). "Shared genetic mutations, particularly in genes encoding ion channel subunits such as CACNA1A, SCN1A, and ATP1A2, further support a common channelopathy model." (PMID 40949139, 2025). "According to Indelicato and Boesch’s intensive study of CACNA1A-related channelopathies, one feasible option is acetazolamide for the chronic or paroxysmal symptoms related to CACNA1A." (PMID 40111503, 2025). "Genetic mutations in KCNA1, CACNA1A, CACNB4, SLC1A3, SCN8A, KCNMA1, and ATP1A3 genes that encode ion channels lend support to the channelopathy theory." (PMID 37008993, 2023). "The underlying channelopathy pathway accounted for 46.7% (7/15) of the monogenic variants, including ion channel genes (SCN1A, KCTD7, KCNC1, CACNA1A, KCNMA1) and ligand-gated ion channel genes (GABRA1, GABRG2)." (PMID 36034301, 2022). "Head trauma triggering is common not only to channelopathies such as CACNA1A, but also to other rare neurological conditions such as vanishing white matter disease, and it does not seem to be completely explained merely by a metabolically stressful situation." (PMID 34708008, 2021). "If EIEE42 has to be considered a separate “epileptic” entity or rather an age-dependent manifestation of CACNA1A channelopathy will be part of the future studies." (PMID 33544220, 2021). "Acute and chronic phenotypes of patients with PMM2-CDG or CACNA1A channelopathies show similarities." (PMID 29470411, 2018). "Section "KCNA1 mutation" describes the observed changes for the KCNA1 mutation that causes a loss of function channelopathy on the Kv1.1 channel, whereas Section "CACNA1 A rocker and tottering mutations" explores the effects of the tottering and rocker mutations of the CACNA1A gene." (PMID 40526235, 2025). "Despite the expanding knowledge on molecular genetics and clinical presentation of CACNA1A variants, the lack of prospective data from large collectives limits our understanding of this channelopathy." (PMID 33737904, 2021). "This merely mirrors the sex distribution of the cohort followed at our institution and constrains the generalizability of our findings to CACNA1A- and GAA-FGF14-related channelopathies in their entirety." (PMID 41240219, 2025). "In the present study, we investigated whether advanced, objective rsEEG analysis can identify disease-specific electrophysiological signatures in CACNA1A- and GAA-FGF14-related disorders—two channelopathies with overlapping clinical phenotype." (PMID 41240219, 2025).